TNF (tumor necrosis factor)
Diseases named in the same sentence as TNF in open-access papers (continued):
Sharing a sentence is not in itself a finding about the gene and the disease.
metabolic disorders (continued). "In this metabolic disorder, pro-inflammatory cytokine expression is stimulated by both ROS and adipose tissue, including tumor necrosis factor-alpha (TNF-α) and interleukins 1 (IL-1) and 6 (IL-6), thereby amplifying OS." (PMID 41128021, 2025). "HD predominantly influences physiological health through its role in inflammatory response (CRP, IL-6, TNF-α), oxidative stress, and metabolic disorders." (PMID 40191209, 2025). "Chronic inflammation is a major cause of metabolic diseases, and olive oil’s phenolic compounds have been shown to have potent anti-inflammatory effects by lowering CRP, TNF-α, and IL-6 levels." (PMID 40136590, 2025). "Key cytokines involved include TNF‐α, IL‐6, and IL‐1β, which are pivotal in the interplay between metabolic disease, inflammation, and carcinogenesis." (PMID 40661794, 2025). "Increased serum levels of pro-inflammatory cytokines such as tumor necrosis factor-alpha (TNF-alpha) and interleukin-6 (IL-6) have been documented in patients with metabolic disorders." (PMID 38409315, 2024). "Its mechanism involves mediating the activation of the PI3K/Akt signaling pathway, inducing VEGF expression, correcting bone metabolism disorders, and downregulating inflammatory factors like TNF-α and RANKL." (PMID 38970109, 2024). "Previous animal studies have shown that the obese pigs with metabolic disorders had elevated levels of proinflammatory macrophages and TNF-a expression in PRF and more ROS in kidney compared to lean pigs." (PMID 39219990, 2024). "Connected with MyD88 and TLR signaling genes (TNF-α, IL-6, IL-12);Participates in metabolic disease(TGF-β1)." (PMID 39911236, 2024). "IL1β, IL6, and TNFα are cytokines that are well identified as the inflammation markers involved in the metabolic disease of fish." (PMID 38671834, 2024). "Inflammatory signaling pathways (such as JNK and IKK) and inflammatory cytokines (such as TNF-a and IL-1b) have been reported to be involved in the pathogenesis of metabolic diseases." (PMID 37762143, 2023). "Tumor necrosis factor alpha (TNF-α) is an inflammatory cytokine which is involved in immune function and is also proposed to play a role in metabolic disorders." (PMID 36826005, 2023). "In this study, Glycitin effectively reversed the TNF-α-mediated loss of Col-2 and Aggrecan, and reduced the level of MMP-13 and ADAMTS-5, suggesting that Glycitin is a key role in metabolic disorders of IVD." (PMID 38019477, 2023). "At the same time, Allobaculum was shown to be negatively correlated with the pro-inflammatory cytokines TNF-α and IL-6, while Blautia can attenuate inflammatory and metabolic diseases, demonstrating that Allobaculum and Blautia have anti-inflammatory effects." (PMID 36673366, 2023). "These cytokines, such as TNFα and IL-6, play a crucial role in the development of metabolic diseases." (PMID 37849923, 2023). "In general, OCA improved mucosal barrier function, down-regulated the concentrations of TNF-α and LPS, decreased the richness and diversity of the gut microbiota in the ileum, and reversed metabolic disorders." (PMID 35770078, 2022). "Studies have shown that the AZGP1 gene can be inhibited by TNF-alpha and other genes related to the development of metabolic disorders." (PMID 35804531, 2022). "The previous studies also revealed that PIC has a therapeutic role especially in metabolic disorders like antioxidant (through lowering ROS), anti-inflammatory (through lowering IL-6, TNF-α), and by suppressing the cytokine signaling pathways." (PMID 35330107, 2022). "In contrast, B‐2 cells release inflammatory cytokines including TNF‐α, and they exacerbate metabolic disorders." (PMID 35005845, 2022). "Pro-inflammatory cytokines promote the recruitment the macrophage and secretion of TNF to act on metabolic diseases including insulin resistance, β cell dysfunction, impaired glucose tolerance, and tissue remodeling." (PMID 36428983, 2022).
metabolic disorders (continued). "Proinflammatory cytokines act on metabolic diseases by facilitate recruiting macrophages and secreting TNF." (PMID 36428983, 2022). "Excess adipose tissue increases the production of pro-inflammatory factors such as leptin, tumor necrosis factor-α, interleukin-6, and resistin which contribute to the development of various metabolic diseases." (PMID 35287586, 2022). "One of the signaling molecules that are produced by adipose tissue is TNF-α, which has been proven to regulate almost every aspect of adipose biological processes as well as metabolic diseases." (PMID 33954196, 2021). "The proinflammatory media models elevated TNF-α, which is produced normally by adipocytes, but is highly elevated through the influence of macrophages that infiltrate adipose tissue in metabolic disease, T2D, and NAFLD." (PMID 34162924, 2021). "Results of the study of hormonal and metabolic disorder connections in ACC patients have revealed higher tumor necrosis factor alpha (TNF-α), interleukin 6 (IL6) and monocyte chemoattractant protein 1 (MCP1) levels." (PMID 33578890, 2021). "This dysfunction promotes metabolic disorders via a mild, chronic inflammation which is characterized by an increased expression of pro-inflammatory factors such as leptin, TNFα, IL6 or monocyte chemoattractant protein-1 (MCP-1 — also known as CCL2)." (PMID 34646852, 2021). "Epidermal growth factor receptor (EGFR) was proposed to be involved in the pathway of metabolic disorders, and tumor necrotic factor-α (TNF-α) was regarded as an early inflammatory biomarker for MetS." (PMID 34564376, 2021). "Inflammatory markers were WBC, CRP, IL-6 and -8, TNF-alpha and fibrinogen, and comorbidities comprised a broad panel including cardiac and metabolic disorders." (PMID 32601330, 2020). "Increasing evidence suggests that inflammatory cytokines, such as tumor necrosis factor alpha (TNFα), play a pivotal role in the induction of vascular dysfunction in cardiovascular and metabolic diseases." (PMID 32190663, 2020). "Proinflammatory cytokines such as IL-6 and TNF, can dramatically mediate metabolic disorders as well as enhance catabolism of OA joint tissue." (PMID 33036557, 2020). "The production of ceramide in the liver increased the secretion of cytokines such as IL-6, TNF-α, and IL-1β, which should contribute to enhancing inflammatory responses in metabolic diseases." (PMID 32547402, 2020). "The literature will state however that IL-6 and TNF-α are often significantly higher in people with a range of metabolic disorders." (PMID 32443433, 2020). "Humans with metabolic diseases have increased plasma concentrations of tumor necrosis factor-α (TNF-α), interleukin-6 (IL-6), IL-1β, C-reactive protein and other inflammatory mediators." (PMID 33776749, 2020). "Serum interleukin-1, interleukin-6, tumor necrosis factor, haptoglobin, serum amyloid A and lactate were increased in cows with metabolic diseases from −8 and −4 weeks before calving, as well as during and after diagnosis of the disease." (PMID 30889779, 2019). "Vast pharmacological efforts have been invested in developing treatments for metabolic diseases by focusing on pro-inflammatory cytokines as TNF-α, IL-1β, and IL-61,2,33,34." (PMID 30996248, 2019). "During the development of metabolic disorder, adipose tissue is considered to be a major source of inflammatory mediators, such as TNF-α, IL-1β, IL-6 and IL-17, which negatively affect adipocyte function." (PMID 30709353, 2019). "Adipocytes play a pivotal role in metabolic disease by promoting chronic inflammation via release of FFAs in response to increased circulating levels of TNF." (PMID 31921154, 2019). "Activated M1 macrophages in adipose tissue aggravate metabolic disorder through the secretion of several inflammatory molecules, such as TNF-α and IL-1β." (PMID 31805752, 2019).
metabolic disorders (continued). "Inflammatory cytokines, including MCP-1, IL-6, IL-8, and TNF-α, which are secreted by adipose tissue, make major contributions to adipose tissue dysfunction and metabolic disorders." (PMID 31871428, 2019). "In transition dairy cows, once mobilized NEFA reach the liver, the TNF-α decreases liver glucose production and increase the triglyceride accumulation which can promote metabolic disorders." (PMID 31311492, 2019). "In the meantime, metabolic disorders can create various pathological products, such as tumor necrosis factor (TNF) and interleukin-1 (IL-1)." (PMID 29805466, 2018). "We used TNF-α, a pro-inflammatory cytokine involved in various inflammatory, atherosclerotic and metabolic disorders, to induce inflammation in these cells." (PMID 28972997, 2017). "TNFα is known to be a key pro-inflammatory marker, contributing to the chronic low-grade inflammatory state observed in human with metabolic disease." (PMID 28632778, 2017). "The main finding of the review was that the serum level of CoQ10 were significantly improved and TNF-α level was significantly decreased in CoQ10 supplementation group compared with placebo group in patients with metabolic diseases." (PMID 28125601, 2017). "There is a clear association between the inflammatory biomarkers used to calculate the DII score (CRP, IL-1β, IL-6, TNF-α, IL-4, and IL-10) and cardio-metabolic diseases such as obesity, diabetes, or CVD." (PMID 27527152, 2016). "Pro-inflammatory cytokines, including tumor necrosis factor α (TNFα), interleukin-6 (IL-6) and interleukin-1β (IL-1β), have shown to deteriorate normal cellular functions, leading to the metabolic diseases." (PMID 27338466, 2016). "In fact, a number of systematic reviews have shown the association between inflammatory biomarkers, such as CRP, IL-1β, IL-6, TNF-α, IL-4, or IL-10, and cardio-metabolic diseases." (PMID 27527152, 2016). "Additionally, studies have reported that TNF‐α gene knockout improves insulin sensitivity in obese mice, suggesting its central role in metabolic disorders." (PMID 41388732, 2026). "In particular, increased levels of cytokines such as TNF-α, IL-1β and IL-17 are present in both HS and metabolic disorders, supporting this hypothesis." (PMID 40217596, 2025). "Furthermore, significant inflammatory biomarkers, such as C-reactive protein (CRP), interleukin-6 (IL-6), and tumor necrosis factor-alpha (TNF-α), have been associated with both HT and metabolic disorders." (PMID 40362879, 2025). "Moreover, in obese individuals, visceral adipose expansion leads to the release of high levels of leptin, resistin, TNF-α, and IL-6, and low levels of adiponectin, which promote inflammation and metabolic disorders." (PMID 40095937, 2025). "Conversely, increased FBN1 signaling has been associated with pro-inflammatory microenvironments in metabolic disease, suggesting that elevated FBN1 may exacerbate TNF-α-mediated neuroinflammation." (PMID 41399726, 2025). "On the other hand, patients with a high BMI have more adipose tissue and, consequently, secrete greater amounts of adiponectin, IL-6, and tumor necrosis factor, resulting in metabolic disorders and a decrease in skeletal muscle mass, making these patients more prone to frailty." (PMID 40779600, 2025). "While low levels of TNF-α can promote metabolic activation, chronic or excessive exposure often impairs adipogenic differentiation and alters lipid synthesis pathways, contributing to inflammatory and metabolic disorders." (PMID 40227405, 2025). "Patients with metabolic disorders have significantly higher levels of TNF-α and IL-6." (PMID 40837641, 2025). "GM dysbiosis and inflammation also induce epigenetic alterations in cytokine genes, such as IL-1β, IL-6, TNF-α, NF-kB, BTLA, IL-18R1, TGF-β, P13k/Akt1, Ctnnb1, and Hsp90aa1, as well as DNMTs, HDACs, and DAT1 associated with the development and progression of metabolic disorders and/or NPDs." (PMID 41228440, 2025).
metabolic disorders (continued). "Second, integration of objective biomarkers of inflammation (e.g., CRP, IL-6, TNF-α) could help clarify mechanistic pathways linking metabolic disease and psychiatric comorbidity." (PMID 41149069, 2025). "As clinical research continues to shed light on the role of TNF-α in these metabolic disorders, it becomes evident that addressing inflammation might be crucial for managing and preventing T2DM and associated conditions." (PMID 40002771, 2025). "LPS is a major factor in bacterial pathogenesis and can cause a series of inflammatory responses in the body, including the release of inflammatory factors such as TNFα, IL1β and IL6, causing a variety of inflammatory symptoms such as metabolic disorders, fever and circulatory disturbances." (PMID 38504633, 2024). ",34 described this type of inflammation as metabolic inflammation, and they found that obese mice released more Tumor Necrosis Factor (TNF) in adipose tissue, resulting in poor insulin sensitivity and glucose homeostasis, thus linking inflammation with metabolic disorders." (PMID 38875754, 2024). "In addition, we also found that Glycitin alleviated TNF-α-induced metabolic disorders, extracellular matrix degradation, oxidative stress, inflammation responses, and mitochondrial damage." (PMID 38019477, 2023). "Studies have shown that non-responsiveness to anti-TNFα is, however, associated with a Th17-cell signature, potentially, indicating that T cells from these individuals suffer from a metabolic disorder that is distinct from anti-TNFα responder patients." (PMID 36311757, 2022). "The accumulation of macrophages in various tissues of obese mice and humans and the increase in macrophage-derived pro-inflammatory cytokines, such as TNF-α in the circulating blood, are the starting point of the chronic low-grade inflammation that contributes to metabolic diseases." (PMID 36015301, 2022). "As the most important component of bacterial endotoxin, LPS has been shown to aggravate metabolic disorders by elevating IL-1β, TNF-α, and IL-6 expression, which might be related to TLRs." (PMID 35774596, 2022). "GrimAge residuals showed associations with a broad range of blood-based biomarkers implicated in age-related disease and premature mortality risk, including inflammation (CRP, WBC, IL-6, and TNF-α), oxidative stress (GGT), neuropathology (GFAP), and metabolic disease (MetS)." (PMID 36153327, 2022). "This poses the question of whether there is a shift from SAT to VAT as the main source for TNFα expression as the metabolic disease transpires." (PMID 35872989, 2022). "In concurrence with metabolic dysfunctions, overfeeding has been well accepted to trigger an inflammatory response, and the release of inflammatory factors such as TNF-α, IL-1β, CRP, and soluble adhesion molecules have also been causally linked to metabolic disorders." (PMID 35126096, 2021). "Interestingly, saturated fatty acids were found to induce the release of pro-inflammatory cytokines, such as IL-6, IL-1β and TNF-α, from immune cells into blood circulation, particularly in individuals with metabolic disorders." (PMID 34681074, 2021). "For T2DM, RSV was revealed to alleviate cardiomyocyte inflammation, mitochondrial dysfunction, and metabolic disorders by downregulating tumor necrosis factor-α (TNF-α)/nuclear factor kappa B (NF-κB) signaling and by preventing palmitoyl-CoA (P-CoA) respiratory sensitivity in cardiomyocytes." (PMID 32256959, 2020). "TNF-α is involved with multiple functions and plays a variety of roles in metabolic disorders." (PMID 31736870, 2019). "Further study is necessary to determine whether TNF-α inhibition can help in the management of human metabolic disease." (PMID 31736870, 2019). "Increased visceral fat is related with metabolic diseases and inflammation, in association with an increased concentration of pro-inflammatory leptin, TNF-α, and IL-6 by increased adipose tissue, rather than subcutaneous fat." (PMID 30558262, 2018).
metabolic disorders (continued). "To translate our findings in vivo, we performed a time-resolved study assessing the effects of imatinib on macrophages and metabolic disease manifestations in HFD-induced obese mice: Reduction of TNFα in peritoneal and liver macrophages occurred most rapidly upon imatinib." (PMID 30333571, 2018). "Taken together, our findings suggest that MTMR14 deficiency evokes severe inflammation via the up-regulation of TNF-α and IL-6, and the metabolic disorders may depend on elevated leptin and decreased adiponectin." (PMID 26697164, 2015). "Wasting in HIV infected persons could be due to many factors associating low oral intake, malabsorption, endocrine disorders and other metabolic disorders, such as the effect of tumour necrosis factor (TNFa)." (PMID 22368758, 2012). "The first factor at the crossroads of inflammation and metabolic disease was TNF-α." (PMID 21716679, 2011). "Therefore, inhibition of TNF-α, IL-17 and IL-23 could alleviate or protect against metabolic disorders, but the data are still limited and conflicting, but obviously needed." (PMID 39331218, 2024). "Additionally, IL-1β and TNF-α levels are chronically raised in metabolic disease." (PMID 36005503, 2022). "The fish oil inhibited inflammatory cytokines, such as tumor necrosis factor (TNF-α) and interleukin-6 (IL-6) levels in patients with NAFLD and other metabolic disorders." (PMID 40416371, 2025). "At baseline, patients exhibited elevated levels of TNF-α and FFA, indicative of significant inflammatory responses and metabolic disorders." (PMID 41244040, 2025). "Elevated TNFα and MCP-1, contributors to metabolic disease progression, classify the increased weight gain in FED-HFD males as an obese state." (PMID 38720938, 2023). "VAT is active in releasing bio-active factors such as leptin, adiponectin, tumor necrosis factor-α, interleukin-6, interleukin-8, and MCP-1 that are involved in the pathogenesis of CVD, metabolic disorders, and T2DM." (PMID 37964956, 2023). "In this context, inflammatory and metabolic diseases are complicated by the presence of molecules such as retinol-binding protein 4 (RBP4), TNF-α, and others that interfere with homeostasis." (PMID 37241737, 2023). "Adipose tissues secrete many inflammatory cytokines such as tumor necrosis factor α (TNF-α) and interleukin 6 (IL-6), which are a group of major contributing factors to metabolic disorders." (PMID 36141228, 2022). "Many studies have shown that pro-inflammatory cytokines and chemokines such as TNF-α, IL-6, MCP-1, and IL-1β in the liver play key roles in the progression of metabolic diseases." (PMID 36676939, 2022). "Therefore, TNF-α may be an early sensitive marker of metabolic disorders during clozapine therapy." (PMID 33774704, 2021). "In the present study, we examined the relationship of LECT2 with TNF-α and MCP-1, which are pro-inflammatory adipokines involved in the development of metabolic diseases." (PMID 28278265, 2017). "Hence, one could speculate that transcriptional downregulation of endocannabinoid-degrading enzymes, possibly in response to later emerging metaflammation as shown for FAAH and TNFα, may represent a critical step in the development of hepatic alteration and metabolic disorder in obese subjects." (PMID 28859076, 2017). "In H9c2 myocardiac cells, TNF-α activates the expression of PGC-1α through NF-κB, resulting in metabolic disorders." (PMID 25738576, 2015). "Numerous CKs, such as tumor necrosis factor alpha (TNF-α), IL (interleukin)-6, CRP, and IL-1β, are studied in the interplay between metabolic disease, inflammation, and carcinogenesis, but mediators of innate immunity, namely inflammasomes, are also regarded with increasing interest." (PMID 39063610, 2024). "Therefore, given its critical relevance in metabolic disorders, we conducted an unprecedented investigation into the serum levels of NOV among CAD patients, as well as its correlation with TNF-α, IL-6, and various biochemical parameters." (PMID 37919772, 2023).